BRAF (B-Raf proto-oncogene, serine/threonine kinase)
Diseases named in the same sentence as BRAF in open-access papers (continued):
Sharing a sentence is not in itself a finding about the gene and the disease.
vitiligo (3 papers, 2019 to 2022). Generalized well circumscribed patches of leukoderma that are generally distributed over symmetric body locations and is due to autoimmune destruction of melanocytes. "The newly utilized keywords included “bevacizumab”, “acquired–resistance”, “BRAF”, “monotherapy”, “vitiligo”, “mutational–landscape”, “mismatch–repair deficiency”, “treatment discontinuation”, “tumor–infiltrating lymphocytes (TILs)”, and “antibiotics”." (PMID 36532038, 2022). "A recently published retrospective series showed a significant association between immune adverse reactions including vitiligo, erythema nodosum, uveitis and keratitis sicca and durable response to BRAF inhibitors either administered alone or in association with MEK inhibitors." (PMID 30939167, 2019).
adenofibroma (2 papers, 2016 to 2025). A benign neoplasm characterized by the presence of connective tissue stroma and epithelial structures. "Sequence analysis revealed no genetic mutations of BRAF or KRAS hotspots, which does not support the hypothesis that mutations of KRAS and BRAF occur at the development of adenofibromas to APSTs." (PMID 27128903, 2016).
anal carcinoma (2 papers, 2014 to 2023). "In the present study we set out to verify the incidence of KRAS, BRAF and PIK3CA mutations in a series of patients with anal carcinoma and analysed the association between these alterations and the clinical-pathological characteristics of patients." (PMID 24642661, 2014). "Our study shows that KRAS and BRAF are not mutated in anal carcinoma, whereas PIK3CA, mutated in about 20% of cases, may represent a mechanism of resistance to anti-EGFR treatment, such as cetuximab." (PMID 24642661, 2014). "In addition, it is notable that the increased expression of upstream activators of ERK (BRAF and MEK1) and of p38 were observed in the tumor microenvironment component of patients with recurrent anal cancer." (PMID 36980587, 2023). "However, the incidence of other gene alterations, e.g. BRAF and PIK3CA mutations, involved in the response to anti-EGFR therapies in colorectal cancer has not been studied in anal carcinoma." (PMID 24642661, 2014).
ascending colon cancer (2 papers, 2020 to 2023). A malignant neoplasm involving the ascending colon. "The patient was diagnosed with cutaneous metastasis of ascending colon cancer with BRAF V600E mutation." (PMID 32481270, 2020). "Herein, we present a very rare case of ascending colon cancer with axillary cutaneous metastasis that was microsatellite instability-high (MSI-H) and harboring a BRAF V600E mutation." (PMID 37962682, 2023).
astroblastoma (2 papers, 2018). "The paradigm for systemic therapy may shift as more is learned about the molecular profile of astroblastomas and targeted therapies such as BRAF inhibitors are considered." (PMID 29708401, 2018).
bowel obstruction (2 papers, 2023 to 2026). "Overall, the status of differentiation grade, initial bowel obstruction, vascular invasion and/or lymphatic infiltration, perineural invasion, pathological T stage, and RAS/BRAF gene mutation were significantly different among the four groups." (PMID 36672503, 2023).
congenital melanocytic nevi (2 papers, 2021 to 2023). "The second was the description of pigmentary and vascular abnormalities in individuals with an entirely distinct mosaic disorder congenital melanocytic nevus syndrome caused by NRAS or BRAF mosaic variants." (PMID 36566878, 2023).
duodenal adenocarcinoma (2 papers, 2021 to 2022). A carcinoma that arises from glandular epithelial cells of the duodenum. "Comparing the 55 patients with duodenal adenoma with the 93 patients with duodenal adenocarcinoma showed significant differences in anatomical location (P < 0.01), treatment methods (P < 0.01), BRAF mutation (P = 0.01), Fn (P = 0.03), and mucin phenotype (P < 0.01)." (PMID 34797780, 2021). "Interestingly, amongst SBA tumors specified as duodenal adenocarcinoma, there appears to be lower frequency of BRAF alterations compared to jejunal or ileal SBAs." (PMID 35267592, 2022). "Conversely, duodenal adenocarcinomas had fewer BRAF (6.3% vs. 12.5%), PTEN (3% vs. 9%), and PIK3R1 (1% vs. 7.5%) gene alterations, as well as lower MSI-high rates (7.3% vs. 9%) and lower overall TMB (8.8 mutations/Mb vs. 11.3 mutations/Mb) compared to other small bowel subsites." (PMID 35267592, 2022). "Although further molecular biological analysis is required to investigate the usefulness of candidate genes other than KRAS and BRAF, assessing KRAS mutation could be a very useful tool for treating sporadic nonampullary duodenal adenocarcinoma." (PMID 34797780, 2021). "However, among the 93 patients with duodenal adenocarcinoma, there were 23 patients with KRAS mutation, and they were significantly different from the 70 patients without KRAS mutation in terms of sex (P = 0.01), BRAF mutation (P < 0.01), and mucin phenotype (P = 0.01)." (PMID 34797780, 2021).
eczema (2 papers, 2023). "Furthermore, eczema (p = 0.07), hearing impairment (p = 0.07), cryptorchidism (p = 0.13), and pulmonary valve stenosis (p = 0.19) were commonly found in patients with MAP2K1/2 variants, while macrocephaly (p = 0.13) was often observed in patients with BRAF variants." (PMID 37697378, 2023).
encephalopathies (2 papers, 2021 to 2025). "In particular, the clinical course of group 1 patients highlights the variable contribution of the “developmental” and “epileptic” component to the “BRAF-related encephalopathy”." (PMID 34573299, 2021).
esophageal melanoma (2 papers, 2015 to 2021). A melanoma affecting the esophageal wall. "Because the data are controversial due to the fact that BRAF/KRAS/KIT coexisting mutations were previously reported, particularly in primary esophageal melanomas, we attempted to explore the possible interaction of these three genes." (PMID 34769348, 2021).
gallstones (2 papers, 2023 to 2025). Solid crystalline precipitates in the biliary tract, usually formed in the gallbladder, resulting in the condition of cholelithiasis. "Moreover, further analysis exhibited that the gallstone rate in the BRAF mutation group (26.7%) was significantly higher than that in the healthy subjects (9.3%)." (PMID 37620872, 2023). "The gallstone rate in the CRC patients (25.0%) and BRAF-positive MSS group (33.3%) was markedly higher than that in the healthy subjects (9.3%)." (PMID 37620872, 2023).
glomerulonephritis (2 papers, 2017 to 2024). A renal disorder characterized by damage in the glomeruli. "We describe a unique case of glomerulonephritis with renal granulomatous vasculitis secondary to the use of BRAF and MEK inhibitors." (PMID 28640105, 2017).
Granuloma (2 papers, 2012 to 2018). A compact, organized collection of mature mononuclear phagocytes, which may be but is not necessarily accompanied by accessory features such as necrosis. "Although there is a case report indicating progression from LCH to LCS and case reports of detection of BRAF mutation in LCS, these two diseases are not in the same spectrum considering age distribution, neoplastic cell morphology, inflammatory granuloma, and cytokine storm release." (PMID 30134914, 2018).
HCMV infection (2 papers, 2012 to 2025). "To examine the contributions that ARAF or BRAF make toward HCMV infection, we targeted their expression via shRNA." (PMID 39902964, 2025). "Given that sorafenib and regorafenib can inhibit other kinases in the RAF1 pathway, including BRAF, we employed other methods to analyze RAF1’s potential contributions to HCMV infection." (PMID 39902964, 2025). "Reduced expression of either ARAF or BRAF did not inhibit infection, suggesting that RAF1 is the most important RAF kinase for productive HCMV infection in fibroblasts." (PMID 39902964, 2025).
Hearing impairment (2 papers, 2023 to 2024). A decreased magnitude of the sensory perception of sound. "Overall, this study shows that knocking out KSR1, as well as inhibiting BRAF, MEK, and ERK, are all promising therapeutic targets to protect from both cisplatin- and noise-induced hearing loss." (PMID 38548338, 2024).
Hepatitis (2 papers, 2021 to 2022). Inflammation of the liver. "We next tested other possible clinical, oncological (BRAF/NRAS status, stage, LDH levels, presence of metastasis), virological or hepatological characteristics of our patient cohorts that might contribute to ICB-hepatitis during dural checkpoint therapy in the pooled cohort." (PMID 36503532, 2022).
hidradenoma (2 papers, 2022 to 2024). A benign epithelial neoplasm arising from the sweat glands. "The three acral hidradenomas were negative for both LR-HPV and BRAF p.V600E." (PMID 39051320, 2024).
leiomyosarcoma (2 papers, 2022 to 2025). An uncommon, aggressive malignant smooth muscle neoplasm, usually occurring in post-menopausal women. "The one patient with BRAF V600E mutation in the uterine sarcoma cohort was diagnosed with uterine leiomyosarcoma." (PMID 36741731, 2022).
lymphatic malformation (2 papers, 2024 to 2025). Primary lymphedema is caused by anatomic or functional defects in the lymphatic system, resulting in chronic swelling of body parts and lymphatic-system malformation. "The somatic activating variant in BRAF (p.V600E) was recently described as a novel cause of macrocystic head and neck lymphatic malformations in three individuals." (PMID 40884273, 2025). "We identified somatic variants within 26 of 44 (59%) individuals with slow-flow anomalies (either lymphatic malformation, venous malformation (VM), or mixed lymphatic/venous malformations) within the genes PIK3CA, TEK, GNAQ, BRAF, GNA11, and PIK3R1 with VAFs ranging between 0.7% to 24.8%." (PMID 39669602, 2024).
mesenchymal neoplasm (2 papers, 2014 to 2025). "The frequency of somatic mutations in the KRAS and BRAF genes varies in tumors of these two subtypes; but it is significantly higher in mesenchymal tumors, and 3 out of 4 BRAF-V600E mutations were discovered in these tumors." (PMID 25157365, 2014).
multinodular goiter (2 papers, 2021 to 2022). Nodular goiter characterized by more than one discrete tissue mass. "This suggests that the natural follicle heterogeneity influences the pattern of BRAF-driven tumor growth in a way that is similar to that of multinodular goiter development." (PMID 34379110, 2022).
multiple sclerosis (2 papers, 2019 to 2023). A progressive autoimmune disorder affecting the central nervous system resulting in demyelination. "Codelivery by a rheumatology professional and a patient (bringing experiential knowledge of RA fatigue) could be evaluated, as could delivery in physical long-term conditions with fatigue (multiple sclerosis, Parkinson’s disease) and the MCID for the BRAF-NRS Effect established." (PMID 30793700, 2019).
Myalgia (2 papers, 2025). "This is consistent with earlier findings where inflammatory side effects, including arthralgias and myalgias, of BRAF and MEK inhibitors were described." (PMID 40536406, 2025). "However, central in this core net one can find the genes NF2 and BRAF (associated to HPO-class BN and ACTH), EP300 (associated to HPO-class BN), AAAS (associated to HPO-class ACTH) and PTPN2 (associated to Myalgia)." (PMID 40831500, 2025).
myxofibrosarcoma (2 papers, 2013 to 2024). A malignant fibroblastic neoplasm arising from the soft tissue. "Typically, myxofibrosarcoma gain and/or amplification was mapped to 7p21.3-q31.1, q31.1-q31.33, q33-q36.2, p21.3, p21.2, p14.1-q11.23, q31.33-q33, p21.2-p14.1, q11.23-q21.3, q36.2-q36.3, which, respectively are known to harbour tumour-associated genes, including TIF, BRAF, MLL3, SMO, and MET." (PMID 24289252, 2013).
ovarian serous cystadenocarcinoma (2 papers, 2022 to 2024). A malignant serous cystic epithelial neoplasm arising from the ovary. "We found that BRAF expression was correlated with pathological stages in several tumor types, including COAD, KIRC, LUSC, and ovarian serous cystadenocarcinoma (OV) (p < 0.05)." (PMID 35910024, 2022).
pancreatic acinar cell carcinoma (2 papers, 2021 to 2022). An adenocarcinoma arising from the pancreas. "A recent case also showed a positive response to combined targeted therapy in patients with pancreatic acinar cell carcinoma with BRAF V600E mutations, who achieved almost complete remission for 12 months." (PMID 35145907, 2021). "In a report analyzing PDAC and pancreatic acinar cell carcinomas, oncogenic BRAF alterations accounted for 13% of the KRAS WT tumors." (PMID 36551707, 2022).
panhypopituitarism (2 papers, 2021 to 2025). Insufficient production of all the anterior pituitary hormones. "DI and panhypopituitarism were more frequent in subjects with API without differences in age, sex distribution, hsCRP, ESR, and BRAF V600E status compared to normal pituitary imaging." (PMID 34439280, 2021).
peripheral sensory neuropathy (2 papers, 2024). "As an example, 1 question asked about a treatment recommendation for a patient diagnosed with metastatic right-sided colon cancer with a BRAF V600E variant who achieved a partial response to 5-fluorouracil, oxaliplatin, and bevacizumab but also developed peripheral sensory neuropathy." (PMID 38888919, 2024).
poorly differentiated thyroid carcinoma (2 papers, 2021 to 2025). "Moreover, due to its histology-agnostic approval for solid tumors with BRAF V600E mutations, this regimen is now also indicated for papillary and poorly differentiated thyroid cancers." (PMID 41368991, 2025).
pulmonary valve stenosis (2 papers, 2022 to 2023). The pathologic narrowing of the orifice of the pulmonary valve. "Case 13 and 17 with BRAF mutation showed pulmonary valve stenosis or HCM." (PMID 35770001, 2022). "Interestingly, BRAF patients were characterized not only by HCM but also by pulmonary valve stenosis, meaning poor prognoses." (PMID 35770001, 2022). "Interestingly, patients with BRAF mutations were not only characterized by HCM, but also by pulmonary valve stenosis." (PMID 35770001, 2022). "BRAF carriers had pulmonary valve stenosis, obstructive HCM, ASD, and mitral regurgitation." (PMID 35770001, 2022).
Rathke's cleft cyst (2 papers, 2016 to 2025). "This proved useful in case 2 when a positive BRAF V600E immunostain followed by a confirmatory BRAF DNA sequencing test helped to lead to the diagnosis of PCP rather than ACP or Rathke’s cleft cyst." (PMID 40444237, 2025).
sarcopenia (2 papers, 2020 to 2022). Progressive decline in muscle mass due to aging which results in decreased functional capacity of muscles. "However, when metastatic CRC patients were excluded, BRAF mutation also associated with myosteatosis alone or together with sarcopenia (p = 0.045)." (PMID 35566781, 2022). "In the four-tiered sarcopenia–myosteatosis variable, neither sarcopenia nor myosteatosis were significantly associated with the BRAF mutation, but when evaluated as separate variables, myosteatosis associated with the BRAF mutation (p = 0.024, data not shown)." (PMID 35566781, 2022). "In multivariate Cox proportional hazards modelling, being dosed ≥2.03 mg/cm2 retained its prognostic significance for both PFS (HR 2.28, 95% CI 1.23−4.09, P = 0.004) and OS (HR 2.53, 95% CI 1.41−4.93, P = 0.002) when also considering advanced age, male sex, LDH, positive BRAF status, and sarcopenia." (PMID 32053287, 2020).
small bowel cancer (2 papers, 2019 to 2024). "In the case of small bowel cancer, which was the second most common non-CRC GI malignancy to have a BRAF mutation in this study, an incidence of 4.0% was detected, which is lower than a prior report suggesting a frequency of approximately 9%." (PMID 38791902, 2024).
struma ovarii (2 papers, 2024 to 2025). An ovarian mature teratoma characterized by the presence of aberrant thyroid tissue. "Notably, this patient presented a rare somatic missense BRAF variant (c.1406G>C, p.Gly469Ala) that was only present in the malignant struma ovarii tumour, being absent in the adjacent (benign) teratoma tissue and in its normal and hyperplastic eutopic thyroid tissues." (PMID 38396644, 2024).
T-cell leukemia (2 papers, 2020 to 2024). A malignant disease of the T-lymphocytes in the bone marrow, thymus, and/or blood. "Notable examples include NOTCH1, PHF6, and FBXW7, which are well-acknowledged for their role in T-cell leukemia, as well as BRAF, which was exclusively predicted in the hairy-cell group, in accordance with its recognized function as a marker for HCL." (PMID 38769532, 2024).
temporal lobe tumor (2 papers, 2020 to 2025). "The left temporal lobe tumor harbored a TERT promoter (TERTp) (variant allele frequency (VAFs): 24.4%) and a BRAF p.Val600Glu (V600E) mutation (VAFs: 17.0%)." (PMID 41473634, 2025).
Thrombosis (2 papers, 2012 to 2019). "As shown by clinical data, we can assume a relationship, which is currently not verifiable, between the intake of BRAF inhibitors and spontaneous rupture of the spleen; also superficial venous thrombosis in the postoperative course has been reported." (PMID 22846499, 2012).
thyroid lymphoma (2 papers, 2023 to 2024). A lymphoma primarily involving the thyroid gland. "Patients with FTC, benign thyroid disease, or thyroid lymphoma were not able to detect BRAF V600E mutations in either tissue or blood samples." (PMID 39061714, 2024).
Tumor Lysis Syndrome (2 papers, 2022). a group of metabolic abnormalities that can occur as a complication during the treatment of cancer, most commonly after the treatment of lymphomas and leukemias. "Although anti-CD20 monoclonal antibody therapy is suggested with BRAF inhibitor in the relapsed setting, we did not include this due to the high disease burden and risk of tumor lysis syndrome." (PMID 36713531, 2022).
urachal adenocarcinoma (2 papers, 2016 to 2025). "This novel approach has revealed that urachal adenocarcinoma is associated with specific gene mutations, including RAS, GNAS, SMAD4, and BRAF, which are absent in bladder adenocarcinoma." (PMID 39778497, 2025).
ZIKV infection (2 papers, 2020 to 2024). "In contrast, BRAF and SOCS2, a FLT3 interactor, were unregulated upon ZIKV infection." (PMID 33148605, 2020). "Based on the observations above drawn from the ZIKV map, we hypothesize that FLT3 or BRAF are the effective targets of Sorafenib in ZIKV infection, rather than VEGFR and PDGFR." (PMID 33148605, 2020).
-only disease (1 paper, 2024). "The TRIPLETE study compared a modified schedule of FOLFOXIRI plus panitumumab to FOLFOX plus panitumumab as first-line therapy for RAS/BRAF wild-type mCRC patients, the majority of whom exhibited multiple metastatic sites (52%), with only 38% of patients having liver-only disease." (PMID 38728364, 2024).
adenocarcinoma in situ (1 paper, 2021). A lesion in which the normally situated glands are partially or completely replaced by atypical cells with malignant characteristics. "Lesions 2 and 5, which had the same histology of adenocarcinomas in situ, harbored the BRAF driver mutation G466E and V600_K601delinsE, respectively, while lesion 6 harbored a BRAF K601E." (PMID 33706781, 2021).
adenopathy (1 paper, 2019). "BRAF mutated tumors were significantly more right-sided, undifferentiated and had more infra and supradiaphragmatic adenopathy." (PMID 31319569, 2019).
adnexal carcinoma (1 paper, 2016). "The patient with a microcystic adnexal carcinoma of scalp who had a BRAF mutation (D22G) showed PD to sorafenib." (PMID 27105424, 2016). "However, the microcystic adnexal carcinoma of scalp patient with a BRAF mutation (D22G) showed PD to sorafenib within 1 month." (PMID 27105424, 2016).
adrenal pheochromocytoma (1 paper, 2015). "In a proteomics screen in PC12 cells (rat adrenal pheochromocytoma) we previously identified MIG-6 as a potential binding partner of BRAF WT." (PMID 26065894, 2015).